RN7SKP70 (RN7SK pseudogene 70)
Gene: Miscellaneous RNA gene on chromosome 5 (178,619,728 to 178,619,998, reverse strand). Ensembl gene ENSG00000252464.
Homologues: Orthologues: mouse Gm55882 (74% identical). Paralogues in human: 7SK (63% identical), RN7SKP180 (63% identical), RN7SKP185 (62% identical), RN7SKP217 (62% identical), RN7SKP243 (62% identical), RN7SKP48 (62% identical), RN7SKP1 (62% identical), RN7SKP127 (61% identical), RN7SKP203 (61% identical), RN7SKP124 (61% identical), RN7SKP176 (61% identical), RN7SKP22 (61% identical), and 284 more.